EPO (erythropoietin)
Diseases named in the same sentence as EPO in open-access papers (continued):
Sharing a sentence is not in itself a finding about the gene and the disease.
anemia (continued). "We hypothesized that critically ill patients requiring mechanical ventilation have an inadequate EPO response to anemia, which contributes to the development and persistence of anemia of critical illness." (PMID 15987387, 2005). "Mechanically ventilated patients demonstrate a blunted EPO response to anemia." (PMID 15987387, 2005). "In addition, patients #5, 6, 8, and 14 with grade 2 anemia received red blood cell transfusions, and patients #4, 5, 13, and 14 received erythropoietin." (PMID 15942626, 2005). "Several studies have shown that the suppressed bone marrow response to anaemia, which is a general feature of malaria, is not caused by insufficient secretion of EPO, but this is disputed by other investigations." (PMID 16321150, 2005). "In patients with normal renal function there is an appropriate increase in erythropoietin in response to anaemia, but in a few cases there may be reduced response of CFU-E to the hormone in vitro." (PMID 7093123, 1982). "In addition, EPO elevation may represent a compensatory mechanism for hypoxia and anemia, which are common in severe infections." (PMID 40114237, 2025). "The authors hypothesised that the increased production of platelets in anaemic patients was related to increased erythropoietin production via cross-reaction with thrombopoietin receptors, and that upregulation of erythropoietin receptors in more severe anaemia would negate this effect." (PMID 41463898, 2025). "However, it is unclear whether this normalization results from the correction of anemia or from a specific effect of erythropoietin itself." (PMID 40230600, 2025). "Indeed, EPO has been used safely in humans for years for the treatment of conditions like anemia." (PMID 40305256, 2025). "Importantly, inflammation may also directly suppress erythropoiesis within the bone marrow, impair erythropoietin signaling, and reduce erythrocyte lifespan, thereby further contributing to perioperative anemia." (PMID 41517510, 2025). "For example, preoperative assessment clinics may flag anemia-dominated patients for mandatory hemoglobin optimization to reach safe thresholds (e.g., >13 g/dL) prior to surgery, supported by intravenous iron supplementation or erythropoietin protocols." (PMID 41302186, 2025). "Early interventions, such as erythropoietin-stimulating agents to address anaemia, bisphosphonates for calcium management, and nutritional support, may improve patient outcomes and mobility by reducing infection risk, potentially lowering VTE risk, similar to effects seen in the general population." (PMID 39941428, 2025). "On the other hand, anemia is a common complication in patients with chronic kidney disease (CKD), as a result of the shortened survival of red blood cells caused by uremia and the relative deficiency of erythropoietin due to insufficient production by the kidneys." (PMID 40218942, 2025). "Therefore, severely increased albuminuria may adversely affect EPO production and iron utilization through inflammation, potentially attenuating the anemia-improving effect of SGLT2 inhibitors." (PMID 40620843, 2025). "In addition, recent studies have identified that uremic toxins, especially indoxyl sulfate (IS), may exacerbate anemia in CKD by disrupting erythropoiesis through EPO-dependent mechanisms, primarily by inducing sub-G1 phase arrest." (PMID 41227308, 2025). "In conclusion, this study indicates that anemia in chronic kidney disease is associated rather than causally driven by complex and possibly dysregulated interactions among erythroferrone, hepcidin, and erythropoietin." (PMID 41227183, 2025). "Therefore, anemia of CRF may be caused by decreased SCFAs produced by F. prausnitzii and decreased EPO production mediated by P. copri through immune mediation, thereby inhibiting erythroid progenitor cell growth." (PMID 40525868, 2025).
anemia (continued). "However, it has been shown that inflammatory anemia responds poorly to EPO in sepsis, and while EPO concentrations may be elevated, they are insufficient to correct anemia and hypoxia." (PMID 40114237, 2025). "Additionally, inflammation can cause direct suppression of erythropoiesis within the marrow, indirect suppression via inhibition of erythropoietin, and reduction in the circulating erythrocyte lifespan, leading to a picture more in keeping with the anemia of chronic disease/anemia of inflammation." (PMID 41517510, 2025). "However, decreased erythropoietin production mediated by renal insufficiency might contribute more importantly than in other forms of anemia of chronic disease." (PMID 41303295, 2025). "In addition to reduced erythropoietin production, the pathophysiological mechanisms of anemia in CKD include uremic repression of erythropoiesis, increased red blood cell destruction, iron and folate deficiency, blood loss from dialysis or uremia, and hypoplastic bone marrow." (PMID 40497218, 2025). "On the other hand, the persistence of anemia regardless of the presence of erythroid hyperplasia suggests ineffective erythropoiesis, which may be due to uremic inhibitors or relative erythropoietin deficiency." (PMID 40497218, 2025). "ESAs may be considered in eligible patients with a serum erythropoietin (EPO) less than 500 mU/mL; however, these agents may not be reimbursed for MF‐associated anaemia in some countries." (PMID 40123795, 2025). "Moreover, kidney damage may indirectly influence bone health and anemia by reducing the synthesis of active vitamin D and erythropoietin secretion, thereby establishing a vicious cycle." (PMID 40635894, 2025). "Despite these results, the cost of EPO relative to transfusion and issues with EPO administration in the outpatient setting, particularly the need for injections multiple times per week, have been cited as reasons that EPO has not become the standard treatment for HS-associated anemia at this time." (PMID 41007072, 2025). "Anemia, similarly, may reflect a multifactorial impairment involving reduced erythropoietin production, iron sequestration, and chronic low-grade inflammation, all of which contribute to reduced exercise tolerance and skeletal muscle hypoxia in elderly patients." (PMID 40566033, 2025). "Furthermore, EPO treatment may mitigate other CKD-related complications beyond anemia, such as cardiovascular disease and proteinuria." (PMID 39200211, 2024). "Although serum concentration of EPO was not available for the dogs of our study, it is plausible that deficiency of EPO may play a role in the pathogenesis of anemia, as the elevated frequency of no-regeneration." (PMID 38787184, 2024). "Exogenous erythropoietin may improve anaemia and outcomes in SCD." (PMID 39267208, 2024). "Additionally, hypoxia secondary to respiratory compromise in severe COVID-19 cases may exacerbate anemia by impairing oxygen delivery to tissues and stimulating erythropoietin production." (PMID 39087175, 2024). "The mechanism underlying the effects of SGLT‐2 inhibition on anaemia has not yet been established, although it has been posited that erythropoietin, which is produced by fibroblasts located in the renal cortex, may play a role." (PMID 39267208, 2024). "The etiology of anemia in CKD patients is intricate and multifactorial; however, inadequate production of erythropoietin alpha (EPO) by the failing kidneys stands as the predominant cause, resulting in disproportionately low levels of circulating EPO relative to the severity of anemia." (PMID 38313992, 2024). "Another clinical trial found that EPO + ATRA could be used to treat patients with MDS anemia in whom erythropoiesis-stimulating agents (ESAs) alone were ineffective, but not in patients with high levels of endogenous EPO, and it did not improve neutropenia or thrombocytopenia." (PMID 39027338, 2024).
anemia (continued). "Furthermore, in recent animal and human studies, anaemia itself has been proposed to increase the risk of NEC, a concept supported by studies demonstrating that the use of erythropoietin (EPO) to treat anaemia may also decrease NEC." (PMID 39649403, 2024). "Reduced endogenous erythropoietin synthesis from renal failure may eventually result in anemia." (PMID 39391392, 2024). "Additionally, bilateral nephrectomy patients may develop anemia, for which Rosacetra has been identified as a potent stimulator of erythropoietin production by the liver and other organs, facilitating erythropoiesis." (PMID 39221033, 2024). "Specifically, anemia-related factors have been shown to increase FGF23 production, including iron deficiency, which is common in adult and pediatric CKD, and increased erythropoietin, levels of which increase in response to decreasing hemoglobin concentrations in mild–moderate CKD." (PMID 37752381, 2024). "We next investigated whether acute anemia induction changes EPO concentration in the BM." (PMID 39284836, 2024). "From a clinical perspective, the risk of compromised bone health should be considered when using EPO to treat anemia in post-operative patients with intertrochanteric fractures of the femur, as it could significantly impact the patient’s recovery and quality of life." (PMID 39278948, 2024). "Anemia in inflammation may be attributed to developing resistance to erythropoietin." (PMID 39493081, 2024). "Moreover, high phosphorus intake results in ineffective erythropoiesis caused by decreased production (decreased RBCs, hemoglobin, hematocrit, and erythroid progenitors in the bone marrow) and increased destruction of RBCs, leading to anemia despite increased EPO secretion." (PMID 39666728, 2024). "Additionally, anemia associated with CKD is a specific form of inflammatory anemia, characterized by the release of cytokines in response to inflammation, which causes progressive loss of renal function and impaired erythropoietin (EPO) synthesis." (PMID 39845803, 2024). "Furthermore, the reduction in systemic inflammation may stabilize erythropoietin resistance, creating a positive feedback loop that facilitates more effective anemia correction." (PMID 39768541, 2024). "Furthermore, it was found that cancer-related anemia may result from erythropoietin inhibition, facilitating the suppression of erythropoiesis by cytokines (IL-6, TNF-α)." (PMID 39372868, 2024). "The role of EPO-EPOR in the pathophysiology of anemia may differ by ethnicity." (PMID 38344715, 2024). "Exogenous erythropoietin administration can increase total FGF23 concentrations in patients with CKD, so it is possible that ESA use may have at least partially mediated the association we observed between anemia and elevated total FGF23 concentrations." (PMID 37752381, 2024). "Besides that, insufficient anemia management with erythropoietin (EPO) was also observed." (PMID 38771822, 2024). "Thus, EPO therapy is commonly used to treat anemia in CKD patients." (PMID 39200211, 2024). "Additionally, renal failure per se contributes to decreased EPO production, leading to anemia." (PMID 37606388, 2023). "It is not surprising to see anemia more commonly among dialysis patients than non-dialysis patients in this study, as the various studies revealed that erythropoietin deficiency and losing blood, either through blood tests or during dialysis were common among dialysis patients." (PMID 36730249, 2023). "Furthermore, anemia and its treatment with EPO both alter iron homeostasis and impact cellular processes that may alter expression of genes typically thought to be stable in the retina." (PMID 37098032, 2023). "Besides RBC transfusion, other treatment options for postoperative anemia may include dietary iron supplementation, intravenous (IV) iron therapy, and recombinant human erythropoietin (rHuEPO) therapy." (PMID 37464433, 2023).
anemia (continued). "In addition, patients with CKD may have inadequate erythropoietin production, and consequential anemia and GIB may be catastrophic in patients who are already anemic." (PMID 37955109, 2023). "Furthermore, anaemia in DN secondary to erythropoietin reduction, uraemic toxin accumulation and dialysis might be responsible for capillary impairment, as stated in previous studies." (PMID 37008921, 2023). "Additionally, the early complete correction of anemia using erythropoietin-stimulating agents does not reduce the risk of cardiovascular events." (PMID 37754834, 2023). "Advanced age, anemia, and absence of adjuvant by erythropoietin may constitute risk factors for the low testosterone level in HD patients." (PMID 38282781, 2023). "Moreover, assessment of serum EPO levels for diagnosis of renal anemia poses a supplementary aspect of future studies, although not recommended to be routinely measured for the diagnosis or management of anemia for patients with CKD." (PMID 37676636, 2023). "In the HF setting, the EPO administration did not prove efficacy on outcome, but the possible benefit linked to the demonstration deserves large-scale trials to examine the effect and safety of anemia treatment in HF patients." (PMID 37374094, 2023). "Moreover, a study reported that anemia is more prevalent in individuals with hemodialysis who suffer from decreasing erythropoietin (EPO) concentrations; nevertheless, increased serum magnesium level appears to reduce the risk of anemia by enhancing EPO response." (PMID 36908911, 2023). "Although the prevalence of anemia is relatively high in developing countries like Ghana, we may not have explicitly considered all hematological parameters like haematocrit, RBCs, erythropoietin, total iron binding capacity, transferrin saturation and serum ferritin." (PMID 38318113, 2023). "The known mechanisms of anemia in DKD include malnutrition due to insufficient erythropoietic materials (such as iron, folic acid, and vitamin B12), blood loss, chronic inflammation, and dyserythropoiesis caused by decreased secretion or defective action of erythropoietin in the kidney." (PMID 37308973, 2023). "Compared to patients with >20%Arg1, those with ≤20%Arg1 include patients with higher serum EPO levels (12.6 vs. 14.6 mU/ml), lower hematocrit (39% vs. 44%), lower serum hemoglobin (12.4 g/dl vs. 14.1 g/dl) and thus a higher number of patients with anemia (44% vs. 19%)." (PMID 36524315, 2023). "To gain insight into the causes of EPO independence and tumorigenicity associated with loss of FANCA function, we performed whole-exome sequencing (WES) analysis of blasts isolated from the spleen of 5 TgSpi1FA+/+ and 9 TgSpi1FA−/− mice with anaemia and splenomegaly." (PMID 37573408, 2023). "Furthermore, DM could negatively affect the interstitial and peritubular structures of kidney (where erythropoietin is produced), and anemia could be the result of decreased erythropoietin production by kidney failure." (PMID 36894956, 2023). "However, it is important to note that a substantial portion of CKD patients also suffer from iron deficiency anemia, which is primarily independent of deficient kidney erythropoietin production." (PMID 38137939, 2023). "During kidney injury, these cells transdifferentiate into myofibroblasts, thus, the capability of EPO production is forfeited resulting in a diminished stimulation of erythropoiesis in the bone marrow (reflected by a reduced reticulocyte production index), finally leading to anemia." (PMID 37676636, 2023). "Furthermore, HbA1c levels may be misleadingly high due to the combination of anaemia and use of erythropoietin." (PMID 37817166, 2023). "The results of this study show a reduction in hemoglobin levels in arthritic rats, which signifies that anemia may be due to the destruction of premature RBCs in the spleen, a reduction in the erythropoietin levels, and reduced iron loading in the synovial tissue of the reticuloendothelial system." (PMID 37111711, 2023).
anemia (continued). "However, in these patients, anemia was commonly treated by EPO stimulating agents (ESA) or by iron therapy, which could individually affect oxidative status in patients." (PMID 35464768, 2022). "A lack of EPO along with iron deficiency are the factors that contribute to anemia." (PMID 35324651, 2022). "Furthermore, DFO treatment could decrease erythropoietin doses for anemia treatment, especially in patients with lower bone turnover, such as those with serum total alkaline phosphatase levels (< 60 U L−1)." (PMID 36190833, 2022). "DKD-related anemia tends to be more severe and develops earlier in comparison with non-DKD-related anemia on the basis of complex mechanisms, such as the inhibitory effects of inflammatory cytokines, poor response to erythropoietin (EPO), and the loss of EPO in urine." (PMID 35373711, 2022). "Therefore, the association between the degree of inflammation represented by BVAS and HbA1c may not be significant because the enhanced activity of AAV may exacerbate anaemia due to insufficient production of erythropoietin." (PMID 35982401, 2022). "Thus, a reduced level of TRPC6 expression due to the loss of DOT1L in erythroid progenitor cells may result in lethal anemia despite normal EPO signaling." (PMID 35563527, 2022). "Thus, the condition of anemia does not normalize despite the compensation of the EPO deficiency, and, therefore, the persistence of anemia is due to a greater extent to an increase of eryptosis." (PMID 35328440, 2022). "Fourth, relevant factors that may affect the levels of RDW, platelet, and RPR; like iron deficiency anemia, iron metabolism, erythropoietin use, and vitamin B12 shortfall, are not evaluated." (PMID 36204660, 2022). "The etiology underlying this persistent anemia after trauma appears to be independent of plasma erythropoietin, given levels of plasma erythropoietin two to eight times higher than healthy controls after injury with inappropriately low plasma reticulocyte levels." (PMID 35514362, 2022). "The inflammatory process may explain this anemia as the cytokines decrease the erythropoietin levels, disturb the iron homeostasis by several mechanisms, directly prevent the proliferation and differentiation of erythroid cells, and diminish the survival of the red blood cells." (PMID 36078893, 2022). "The implication that endogenous EPO may be sufficient to support tumor growth suggests that targeting EPOR on tumor cells is a relevant approach to attenuate tumor growth while enabling treatment with EPO to alleviate anemia." (PMID 36052260, 2022). "The recorded anemia may be attributed to the inhibition of the erythropoietin hormone, which correlates with Cis-induced kidney damage as the kidney is the major source of the erythropoietin hormone or may be due to the suppression of bone marrow precursors." (PMID 35337092, 2022). "Therefore, data on serum iron, folic acid, vitamin B12, EPO, and other indicators associated with anemia were not collected from all the patients." (PMID 36349057, 2022). "Because the patients receiving S/V therapy with decreasing Hb exhibited higher mortality rates and lower survival rates than did those with stable Hb, we grouped patients by whether they had received such anemia treatment into erythropoietin, folate, vitamin B12, and iron groups." (PMID 35581275, 2022). "This analysis shows that anemia is independently associated with increased risk for all fractures at 10 and 16 years after adjusting for age, year of birth, smoking, hip BMD, falls, stroke, cancer, diabetes, kidney function, testosterone and estrogen levels, CRP, and EPO." (PMID 35739404, 2022). "Thus, anemia in CKD is commonly attributed to erythropoietin insufficiency." (PMID 35622784, 2022). "Anemia can occur in heart failure with or without chronic kidney disease and is likely to be due to increased production of tumor necrosis factor-alfa and interleukin-6, which in turn can cause reduced erythropoietin secretion." (PMID 34978627, 2022).